IL1B (interleukin 1 beta)
Diseases named in the same sentence as IL1B in open-access papers (continued):
Sharing a sentence is not in itself a finding about the gene and the disease.
acute lung injury (42 papers, 2011 to 2025). A condition of lung damage that is characterized by bilateral pulmonary infiltrates (pulmonary edema) rich in neutrophils, and in the absence of clinical heart failure. "We evaluated the levels of key cytokines, including TNF-α, IL-6, IL-1β, IL-10, IL-17, IL-22, IFN-γ, and TGF-β1, which play central roles in the inflammatory cascade associated with LPS-induced acute lung injury (ALI)." (PMID 41280422, 2025). "Pro-inflammatory cytokines such as TNF-α, IL-6, and IL-1β, coupled with the anti-inflammatory cytokine IL-10, have important functions in the inflammatory process that leads to the advancement of acute lung injury (ALI)." (PMID 38732622, 2024). "IL-1-mediated inflammation in COVID-19-associated acute lung injury (ALI) follows the biological path of NLRP3 inflammasome and caspase-1 activation, leading to production of major innate immune mediators, IL-1β and IL-18." (PMID 36979908, 2023). "It was reported that overexpression of miR-146a suppresses the production and secretion of TNF-α, IL-6, and IL-1β to inhibit the development of LPS-induced acute lung injury." (PMID 35112981, 2022). "Recently, we showed that the deletion of Apoptosis signal-regulating kinase 1 (ASK1) protects against hyperoxia-induced acute lung injury (HALI) by suppressing IL-1β and TNF-α." (PMID 27058411, 2016). "ROS drive modifications of IκB proteins, leading to their degradation and allowing active NF-κB translocation to the nucleus and inducing inflammatory cytokine release, such as (TNF)-α, IL-1β, and IL-6, which are involved in the inflammatory process of acute lung injury (ALI)." (PMID 37569801, 2023). "However, the biological mechanisms that activate the IL-1β pathway in acute lung injury (ALI) are still elusive." (PMID 32117318, 2020). "On the other hand, Rg3 was found to decrease the levels of pro-inflammatory mediators (e.g., TNF-α and IL-1β) and increase the production of anti-inflammatory cytokines (e.g., IL-10), resulting in attenuation of damage in lipopolysaccharide-induced acute lung injury in mice." (PMID 31412594, 2019). "This study aimed to evaluate the potential protective effect of Ap against acute lung injury (ALI) associated with HIR, utilizing the Pringle maneuver to induce 30 min of hepatic ischemia followed by 1 h of reperfusion, while targeting the NLRP3/IL-1β signaling pathway." (PMID 41254086, 2025). "In addition, soluble IL-1β bioactivity and autocrine IL-1β-dependent IL-6 up-regulation are critical initiators of fibroblast activation and proliferation that likely play a role in the fibroproliferative response in human acute lung injury." (PMID 21423633, 2011). "AS-IV decreased the levels of TNF-α, IL-6, and IL-1β in serum and BALF of mice with Acute lung injury (ALI)." (PMID 38954702, 2024). "In an LPS-induced acute lung injury mouse model, ILG alleviated the severity of lung injury, reduced the production of IL-1β, and lowered protein levels of NLRP3, ASC, cleaved caspase-1, and pro-IL-1β." (PMID 33535473, 2021). "DHA was previously reported to hinder the production of proinflammatory cytokines IL-1β, TNF-α, and IL-6 via regulating NF-κB signaling in acute lung injury (ALI)." (PMID 34956376, 2021). "In acute lung injury (ALI), Met also reduces the number of inflammatory cells and expression of pro‐inflammatory cytokines such as TNF‐α, IL‐1β, and IL‐6." (PMID 34473417, 2021). "Nilotinib was also reported to reduce IL-6, IL-1β, and TNF-α levels in mice of bleomycin-induced acute lung injury model." (PMID 31293574, 2019). "Acute lung injury (ALI) induced by intestinal ischemia/reperfusion (II/R) has high incidence and mortality, in which IL-1β was essential for the full development of ALI." (PMID 26980948, 2016). "NF-κB activation is a critical transcription factor required for the maximal expression of many inflammatory cytokines and chemokines (e.g., TNF-α, IL-1β, IL-6, and MIP-2) involved in the pathogenesis of acute lung injury." (PMID 23710113, 2013).
acute lung injury (continued). "Besides, accumulating evidences have demonstrated that paeonol and forsythoside A, the effective components in JJJG, can act on the key pathological mechanism of (IL-6, TNF-α, IL-1β)/JAK2/STAT3/VEGF in the treatment of liver cancer and acute lung injury." (PMID 39494342, 2024). "An increasing number of studies have shown that in animal models of ischemia-reperfusion (I/R) and acute lung injury (ALI), NGR1 attenuates the expression levels of the inflammatory factors IL-6, TNF-α, and IL-1β and attenuates injury, leading to interventional protection against the disease." (PMID 38109303, 2023). "Increased miR-150 decreases neutrophil counts and production of inflammatory cytokines IL-1β, IL-6, and TNF-α along with levels of total protein, albumin and IgM in the BAL fluid in LPS-induced acute lung injury mice in vivo, as well as alleviating LPS-induced A549 cell apoptosis in vitro." (PMID 32315984, 2020). "DA could significantly reduce the level of IL-1β, IL-6 and TNF-α in the bronchoalveolar lavage fluid of the LPS-induced acute lung injury mouse." (PMID 26223251, 2015). "The acute lung injury (ALI) mouse model was successfully induced by smoke inhalation, as confirmed by the aberrantly modified cell numbers of red blood cells and neutrophils counts, increased levels of TNF-α, IL-1β, Bax, caspase-7, caspase-3, and decreased Bcl-2 content in lung tissues." (PMID 35152840, 2022).
enteritis (42 papers, 2010 to 2025). Inflammation of the small intestine. "Tumor necrosis factor α (TNF-α) and interleukin 1β (IL1β) are typically pro-inflammatory cytokines, and up-regulation of their gene expression is closely associated with enteritis." (PMID 37520524, 2023). "During enteritis, significant infiltration of inflammation‐associated factors such as TNF‐α, IL‐1β, and IL‐6 causes damage to intestinal epithelial cells, triggering an increase in intestinal permeability." (PMID 40661137, 2025). "Similar results were observed in common carp (C. carpio), where supplementing 300 mg/kg SB alleviated soybean oil-induced enteritis by suppressing il-1β and tnf-α gene expressions and promoting tgf-β gene expression." (PMID 40732103, 2025). "Twelve-week-old A20ZF7Rag1–/– mice exhibited negligible intestinal inflammation and expressed levels of Il1b and Ccl20 similar to those in Rag1–/– mice, suggesting that adaptive lymphocytes are required for enteritis in A20ZF7 mice." (PMID 40892518, 2025). "In this experiment, the levels of TNF-α, IL-1β, IL-6, and IL-10 in the mouse colon were measured using ELISA kits to assess the impact of different treatments on inflammatory factors in murine enteritis." (PMID 39697653, 2024). "Previous studies have shown that probiotics can significantly reduce the levels of IL-1β and IL-6 and increase the level of the anti-inflammatory cytokine IL-10 in the serum of mice with enteritis, thereby alleviating intestinal inflammation." (PMID 37817260, 2023). "By combining network pharmacology with analysis of the targets of active ingredients in purslane and the pathways related to enteritis, we found that genes related to pyroptosis, such as Caspase and IL-1β, play an important role in this process." (PMID 38132483, 2023). "At present, it is known that TNF-α, IL-1β, and IL-6 are known to be closely related to the progression of enteritis." (PMID 36076306, 2022). "Consistently, the serum concentrations of pro-inflammatory cytokines (IL-18 and IL-1β) were significantly increased in LPS-induced mice group, indicating the successful establishment of the enteritis model." (PMID 32950974, 2020). "We demonstrated that expression of TNF-α and IL-1β mRNAs were alldecreased by treating with curcumin or NAC in rat enteritis model." (PMID 20885979, 2010). "High percentage of dietary SBM could induce enteritis in L. crocea, showing increased proinflammatory cytokine production (IL-1β, IL-6, and TNF-α) and decreased anti-inflammatory cytokine expression (IL-4/13a, IL-4/13b, and TGF-β)." (PMID 40688731, 2025). "The cytokines TNF-α, IL-1β, and IL-6 represent critical pro-inflammatory substances of enteritis." (PMID 38998101, 2024). "Additionally, IL-6 and IL-1β are important proinflammatory factors in enteritis that exert pleiotropic effects by participating in immune defense, nerve cell function, and hematopoietic function." (PMID 38346819, 2024). "Studies in aquatic animals have shown that similarly to butyric acid, glutamine and its dipeptide can downregulate the mRNA expression of TNF-α and IL-1β in the intestine of hybrid grouper and turbot, and effectively inhibit the fish enteritis induced by soybean meal." (PMID 37266423, 2023). "Likewise, negative health-related impacts in the gut of turbot were reported after feeding high levels of corn gluten meal, inducing enteritis, and decreasing intestinal immunity, by increasing the inflammatory cytokine transcripts IL-1β, IL-8, and TNF-α." (PMID 35565636, 2022). "The observation that IL-1α and IL-1β is reduced, while IL-1RA is kept high in M. capsulatus primed DC-T cell co-cultures is interesting in the light of M. capsulatus anti-inflammatory effects in a murine enteritis model." (PMID 28293233, 2017).
enteritis (continued). "The levels of IL-1β (p < 0.0001), IL-6 (p < 0.01), and TNF-α (p < 0.0001) in the serum of mice in the enteritis model group were significantly elevated compared with the CON group, indicating that DSS can trigger systemic inflammatory responses in mice." (PMID 40238292, 2025). "IL-6, IL-1β, and TNF-α are considered biomarkers of inflammation and are positively correlated with the severity of enteritis." (PMID 41007944, 2025). "The present study found that treatment of SCP-Se NPs more effectively reduced LPS-induced elevation of IL-1β, IL-6, and TNF-α relative to SCP, closely correlated with its anti-enteritis effects." (PMID 36899787, 2023). "Fraxetin was reported to mitigate the levels of IL-1β, IL-6, TNF-α and prostaglandin E2, improve the content of superoxide dismutase (SOD) and IL-10 in rats with enteritis." (PMID 37161415, 2023). "In the enteritis patient, TNF-α and IL-1β not only increase the infiltration of neutrophils, but also cause damage to the intestinal barrier." (PMID 35401451, 2022). "The levels of IL-1β, TNF-α, NO and PGE2 were decreased compared to those in the Treg-transferred mice and were significantly different compared to the levels in the enteritis group (P<0.05)." (PMID 30364052, 2018). "The number of goblet cells and inflammatory cells was reduced, and the levels of IL-1β, TNF-α, NO, and PGE2 were significantly decreased in the Tregs-infusion group compared to those in the enteritis group (p<0.05)." (PMID 30364052, 2018). "After 24 hours of induction of LPS, enteritis cells could secrete higher inflammatory factors TNF-α, IL-6 and IL-1β." (PMID 40948782, 2025). "In the present study, TS1 also reduced the SE-induced increase in the expression of pro-inflammatory cytokines (IL-1β, IL-6, TNF-α, IL-4, MCP-1) in the intestine and serum, which is consistent with previous findings and observations of lipopolysaccharide-induced enteritis in vitro." (PMID 36759839, 2023). "Furthermore, IL-10 levels were much lower in enteritis mice than in the normal group, while TNF-α, IL-1β, and IL-6 levels were dramatically enhanced after DSS administration." (PMID 37375702, 2023). "Recent studies have shown that IL-1β and TNF-α can be proinflammatory cytokines in IBD, whereas IL-10 has been demonstrated to play a vital role in the control of inflammation and prevention of enteritis." (PMID 31341536, 2019). "BEA can inhibit the expression of L-12, IL-1β, and IFN-γ in enteritis colon tissue with enteritis." (PMID 30515098, 2018). "As to the enteritis-related cytokine, the significantly suppressed tnf-α, which is at the upstream of intestinal pro-inflammatory cytokines (such as the currently revealed downregulated il-1β though not significantly), may play an important role in SN’s ameliorating effect." (PMID 34887862, 2021).
Cirrhosis (41 papers, 2011 to 2025). A chronic disorder of the liver in which liver tissue becomes scarred and is partially replaced by regenerative nodules and fibrotic tissue resulting in loss of liver function. "After adjustment, only IL-1RA (p = 0.007) and IL-1β (p = 0.030) remained statistically significant, indicating their potential role as independent predictors of infection in patients with cirrhosis and acute decompensation." (PMID 41354872, 2025). "Patients with cirrhosis as well as patients with chronic liver diseases are characterized by elevated serum IL-1b levels." (PMID 40565198, 2025). "It is worth noting that within this global immunosuppressed intrahepatic environment, a further reduction in key intrahepatic genes activated in response to microbial components and LPS, including Tlr4 and IL-1β was seen in HCC compared to advanced cirrhosis." (PMID 33858327, 2021). "Many other proinflammatory cytokines, including interleukin IL-1β, IL-18, and TNF-α have been associated with increased risk of progression to cirrhosis." (PMID 29033929, 2017). "Low-grade cirrhosis-associated immune dysfunction is present in cirrhotic patients without ACLF and is characterized by the production of pro-inflammatory cytokines such as Il-1β, IL-6, TNF-α and INF-γ." (PMID 39861356, 2025). "Hence, these findings suggest neutrophils/NETs as a potential source of IL-1b in HBV-mediated cirrhosis." (PMID 40565198, 2025). "Studies have linked the development of cirrhosis-induced cardiac dysfunction with the activation of nuclear factor-κB and subsequent release of proinflammatory cytokines, including TNF-α and IL-1β, which up-regulate inducible nitric oxide synthase and subsequent nitric oxide release." (PMID 40738513, 2025). "Development of cirrhosis in some patients could be related to inflammation mediated by TNFα and IL-1β." (PMID 31118107, 2019). "Similarly, elevated levels of salivary IL-1β, IL-6, and secretory IgA in cirrhosis patients have also been reported." (PMID 29969462, 2018). "SB reduced the serum concentrations of TNF-α, IL-1β, IL-6, and IL-4 in animals with metabolic dysfunction-associated steatotic liver disease (MASLD); lowered the serum TNF-α and IL-6 levels in experimental cirrhosis in rats; and reduced the CRP levels in decompensated cirrhosis." (PMID 39203520, 2024). "Patients with cirrhosis due to viral hepatitis showed increased numbers of hepatic macrophages associated with the infiltration of other pro-inflammatory CD14+HLA-DRhiCD206+ myeloid cells, which in turn produced pro-inflammatory cytokines such as IL-1β, IL-18, and TNF-α." (PMID 36926073, 2022). "Additionally, we found a feedback loop between TSG-6, MMP12 and pro-inflammatory cytokines (TNF-α, IL-6, and IL-1β), which may improve our understanding of the aggravating process of cirrhosis and antifibrotic mechanisms of TSG-6 and MSCs." (PMID 31903104, 2020). "Our study demonstrated that concentrations of IL-17F, IL-23 and IL-1b were significantly lower in patients with acute decompensation and ACLF compared to those with compensated cirrhosis, indicating a progressive decline with increasing disease severity." (PMID 41200179, 2025). "Levels of IL-17F, IL-23, and IL-1β levels were significantly lower in patients with AD and ACLF compared to those with compensated cirrhosis." (PMID 41200179, 2025). "Studies which stimulated monocytes or PBMCs from patients with cirrhosis or healthy controls with LPS ex vivo have indicated higher level of TNF-α, IL-1β and IL-6 production in the former." (PMID 38413535, 2024). "A higher trend of pro-inflammatory cytokines including IL-1α, IL-1β, IL-6, IL-8, IFN-γ and TNF-α was detected in the plasma from ACLF patients than that from cirrhosis patients, as well as the anti-inflammatory cytokines including IL-4, IL-10 and IL-13." (PMID 37380987, 2023).
Cirrhosis (continued). "According to qRT-PCR, levels of the proinflammatory cytokines (IL-1β, TNF-α, and IL-6) were extremely increased in ACLF patients compared with those in HCs and cirrhosis patients, which suggested a hyperinflammatory state in the liver of ACLF patients." (PMID 35629036, 2022). "Patients with decompensated cirrhosis presented a more limited alteration in TLR signalling genes, including 6 of the 17 upregulated genes observed in compensated cirrhosis, SIGIRR, IRAK1, HSPA1A, TOLLIP and ELK1, as well as downregulation of IL-1B." (PMID 34774066, 2021). "There was a significant increase in IL-1β and MCP-1 mRNA expression in mice with vagotomy compared to the controls, which marginally changed after the development of cirrhosis." (PMID 34248683, 2021). "In hepatitis C virus infection, studies show that serum IL-18 and IL-1β concentrations are higher in patients with chronic HCV infection and HCV-related cirrhosis compared with healthy controls." (PMID 34161370, 2021). "When comparing advanced cirrhosis with HCC time points, a further reduction in several proinflammatory cytokines including Tlr4 and IL-1β was seen (P = 0.0037 and P = 0.0032, respectively)." (PMID 33858327, 2021). "Growing evidences revealed higher levels of IL6, TNFα, IL1β, and IL10 in HCC patients with cirrhosis compared with those infected with HBV or HCV in the absence of cirrhosis." (PMID 32164265, 2020). "Cirrhotic rats had significantly higher levels of proinflammatory cytokines including TNF-α, IL-1β and IL-6, and soluble ICAM-1, which have been shown to play important roles in development of cirrhosis." (PMID 22022478, 2011). "In this prospective observational study, we analyzed circulating levels of IL-23, IL-17A, IL-17E, IL-17F, IL-1β, and IL-1RA in 127 patients with compensated cirrhosis, acute decompensation (AD), or ACLF in the absence of active infection." (PMID 41200179, 2025). "For example, activated hepatic macrophages produce cytokines, such as IL-6, IL-1β, TNF-α and macrophage colony-stimulating factor (M-CSF), which sustain their pro-cirrhosis and pro-inflammatory activities while also stimulating HSCs to form an inflammatory cascade." (PMID 38275754, 2023). "Prior to the presence of cirrhosis, in ARLD and NAFLD, hepatic macrophages become activated by LPS, IFN-ɣ, and GM-CSF signalling and show pro-inflammatory cytokine/chemokine secretion (IL-6, IL-1β, and CCL2)." (PMID 36926073, 2022). "Our findings indicate that the effect of these SIM may either not translate from in-vitro to patients with cirrhosis, or the impact of TNF-α and IL-1β could be limited to their secretion by astroglial cells and thus not translate to measurably different levels in cubital vein blood." (PMID 39656322, 2024).